INS (insulin)
Diseases named in the same sentence as INS in open-access papers (continued):
Sharing a sentence is not in itself a finding about the gene and the disease.
Insulin resistance (continued). "We report on effects of the vegetable on a HF diet induced fat accumulation, insulin resistance, inflammation, endotoxemia and the expression of genes encoding proteins that are involved or impact the insulin signaling pathway in the skeletal muscle of C57BL/6J mice." (PMID 32290353, 2020). "Hence, defects in insulin-stimulated muscle glucose uptake are considered a principal component of typical obesity-associated insulin resistance." (PMID 32977552, 2020). "In another Chinese study (but, in this case, on overweight and obese patients), PN levels were again positively and significantly associated with WC, fasting insulin, homeostasis model assessment-insulin resistance (HOMA-IR), AST, ALT, and γ-glutamyltranspeptidase (GGT)." (PMID 33255560, 2020). "Therefore, to further evaluate the molecular mechanism underlying the HFD-induced brain insulin resistance, we investigated the insulin signaling pathway through Western blotting and immunostaining analyses." (PMID 31963819, 2020). "Four different SMPs are related to %BF in men (rs59634436, rs10033691, rs11937052, and rs17041272), of which only rs17041272 has been studied for its participation in insulin sensitivity in the Spanish population; results show this SNP to be at risk for insulin resistance." (PMID 33158152, 2020). "Therefore, insulin deficiency or impairment of insulin signaling (namely, insulin resistance) in the central nervous system (CNS) can result in brain disorders." (PMID 32581820, 2020). "It has been proved that miR-145, miR-126 and miR-96 cause impaired insulin signaling and insulin resistance by targeting Insulin Receptor Substrates 1 and miR-152, miR-20a-5p and miR-19a regulates hepatic glycogen synthesis by targeting Phosphatase and Tensin Homolog." (PMID 32342229, 2020). "Increased β-cell mass and insulin secretion were observed in diet- and gene mutation-induced obese mice, which may compensate for the increased metabolic demand because of insulin resistance under the obese state." (PMID 33088334, 2020). "Insulin resistance is regarded as a primary causative factor and pathophysiological basis of metabolic syndrome; and it has been demonstrated that increasing insulin sensitivity could significantly alleviate those diseases associated with metabolic syndromes." (PMID 32098371, 2020). "After 4 weeks of HFD‐feed, the plasma insulin value was higher from 1.72 ± 0.058 to 2.61 ± 0.088 mIU/L (p < 0.001) in the control to the T2D groups, respectively, which evidenced the condition of hyperinsulinemia caused by insulin resistance." (PMID 33103024, 2020). "It has been hypothesized that CNS insulin resistance may play a causal role in both the development and the progression of AD, consistent with insulin’s role in brain metabolism and neuronal survival." (PMID 32226608, 2020). "The involvement of insulin signaling on brain mechanisms related to depression indicates that insulin resistance may be one of the main pathogenic drivers for NAFLD." (PMID 33537324, 2020). "In children, high levels of leptin and insulin are often associated with low levels of adiponectin and high levels of resistin, as obesity is a condition that modulates the secretion of both adipokines, which exacerbates insulin resistance." (PMID 33266497, 2020). "In addition, PM2.5 exposure causes vascular insulin resistance and suppresses insulin-stimulated endothelial nitric oxide synthase (eNOS) phosphorylation (likely an endothelial-specific event)." (PMID 33276797, 2020). "Alternations in both insulin secretion and insulin resistance may be considered as risk factor for developing PTDM." (PMID 32245262, 2020). "Though impaired β-cell function and insulin resistance are the 2 major causes in the pathogenesis of T2D, East Asian populations tend to display relatively lower β-cell function and insufficient insulin secretion, so they are considered as having higher T2D predisposition than white populations." (PMID 33296380, 2020).
Insulin resistance (continued). "In addition, loss of leptin‐induced insulin‐sensitising effects assists in the development of insulin resistance and hyperinsulinemia." (PMID 31880032, 2020). "The altered adipokines and pro-inflammatory cytokines such as IL-6, TNF-α, and MCP-1 which secreted from adipose tissue may directly or indirectly caused insulin resistance through impairing insulin signaling or activating pro-inflammatory pathways." (PMID 32265835, 2020). "Therefore, even though high-fat diets are associated with insulin resistance, the supplementation of a diet with slow digesting carbohydrates had a beneficial effect by improving the insulin response in these muscles." (PMID 32092940, 2020). "In addition, increment of insulin secretion is partly associated with pancreatic islet hyperplasia during the development of insulin resistance." (PMID 32947952, 2020). "Absolute deficiency of insulin in type 1 diabetes or insulin resistance in type 2 diabetes could diminish GLUT4‐mediated uptake of glucose from bloodstream in skeletal muscle, leading to reduced glucose load in myocytes." (PMID 32253813, 2020). "Also, high dietary IL and II can be linked to β-cell dysfunction and increased insulin resistance through influencing insulin secretion." (PMID 33008356, 2020). "We also did a functional enrichment analysis of DEGs in pancreatic, skeletal, and adipose tissue showing overlap with the HOMA-β-associated genes, and found that they enriched the Insulin Signaling and Insulin Resistance pathways in skeletal muscles and adipose tissues." (PMID 32294959, 2020). "Such an impairment of the PI3K-Akt pathway is also associated with deterioration of insulin resistance, which may be restored by insulin therapy." (PMID 32993618, 2020). "These signaling pathways, which may be activated by TNFα, free fatty acids, ROS, and hypoxia, cause serine kinase phosphorylation of IRS-1 or IRS-2, which blocks insulin signaling and subsequently, causes insulin resistance." (PMID 32971975, 2020). "In addition, several studies concluded that increasing plasma POA level lowered fasting insulin, insulin resistance and the risk of type 2 diabetes; this has been verified by cell experimental studies." (PMID 31690987, 2020). "We found higher insulin dose, suggesting insulin resistance, to be associated with decreased CCA." (PMID 32063882, 2020). "Type 2 diabetes (T2D) results from defects in insulin secretion, deficiency in insulin signaling and/or insulin resistance that may contribute to chronic hyperglycemia." (PMID 33269015, 2020). "Overexpression of miR-29a/b/c in 3T3-L1 adipocytes could largely repress insulin-stimulated glucose uptake through inhibiting Akt activation and cause insulin resistance." (PMID 33195407, 2020). "Type II diabetes or adult- onset diabetes (about 90% of cases) is characterized by an impairment of homeostasis of glucose and insulin, in particular, the development of insulin resistance of target tissues associated with compensatory hyperinsulinemia, followed by beta-cell dysfunction." (PMID 32911736, 2020). "Increasing the daily insulin dose might, however, increase insulin resistance, resulting in a high hypoglycemia risk and an increase in body weight." (PMID 32351447, 2020). "In addition, ucOC correlated with AUCins/gluc and ISSI-2, and this finding reflects the association between ucOC and insulin secretion in the early and late phases and accounts for the compensatory capacity against insulin resistance." (PMID 32821293, 2020). "In obesity pro-inflammatory chemicals which released from the accumulated abdominal fat and make the body less sensitive to the insulin and disrupt the function of insulin responsive cells, known as insulin resistance which leads to oxidative stress, often linked to the development of T2D3." (PMID 33037249, 2020).
Insulin resistance (continued). "Aging is associated with increased insulin levels and insulin resistance, but a comparison between mice aged 3 and 10 months suggested that hyperinsulinemia associated with this aging period is related to increased insulin secretion and not reduced insulin clearance." (PMID 32860984, 2020). "In addition, systemic insulin resistance (i.e., elevated fasting blood glucose and insulin levels) is associated with the development of pulmonary arterial hypertension and treatment with PIO abnormal pulmonary artery muscularization." (PMID 33192545, 2020). "Literature review helped us to hint that altered levels of most metabolites might associate to insulin sensitivity and insulin resistance in MHO and MUHNO individuals, respectively." (PMID 32405361, 2020). "So, it is predicted that PUFAs may reduce the risk of insulin resistance by increasing membrane surface receptors and increasing insulin entry into the cells." (PMID 33109143, 2020). "The caffeinated energy drink consisting of 32 mg/100 mL caffeine, 400 mg/100 mL taurine and 31 mg/100 mL glucuronolactone resulted in elevations in insulin that caused a greater modified homeostatic model assessment of insulin resistance (HOMA-IR) score, indicating greater insulin resistance." (PMID 33339359, 2020). "Normal pregnancy is associated with insulin resistance and with pregnancy progression, where insulin sensitivity may gradually decline to 50% of the normal expected value." (PMID 32090124, 2020). "Interestingly, they demonstrated that LDL-ceramide caused whole-body insulin resistance in lean mice, an effect mediated by a decrease of insulin signal in skeletal muscle." (PMID 32849282, 2020). "A recent longitudinal multi-omics study described associations between inflammatory markers and insulin resistance, and furthermore demonstrated differences between insulin-sensitive and insulin-resistant individuals in the molecular responses to stress events such as respiratory viral infections." (PMID 33261667, 2020). "As insulin resistance is associated with an imbalance of the autonomic system, insulin could indirectly modulate the RTG and Tmax through sympathetic system stimulation." (PMID 32377524, 2020). "All of these pathways can inhibit insulin signal transduction and cause insulin resistance." (PMID 32774144, 2020). "Hyperinsulinemia, or excess secretion of insulin, is thought to cause insulin resistance, via unknown mechanisms." (PMID 33038072, 2020). "High IGF-1 levels could increase insulin sensitivity, while insulin resistance has been associated with lower IGF-1 and enhanced metabolism of HDL particles by hepatic lipase." (PMID 33101407, 2020). "The accumulation of Fe in the liver may cause insulin resistance by interfering with the ability of insulin to inhibit hepatic glucose production." (PMID 33050015, 2020). "Interestingly, the chronic administration of olanzapine is associated with the development of hyperinsulinemia and insulin resistance; the decrease in insulin sensitivity was reported in 29 healthy individuals after 10 days of olanzapine treatment (10 mg/day)." (PMID 32373066, 2020). "Similarly, although a positive association between elevated fibrinogen levels and insulin resistance has been reported, the relationship between hyperfibrinogenemia and insulin responsiveness remains unresolved." (PMID 32879892, 2020). "Interestingly, TRIB3 has been shown to be higher in the skeletal muscle of insulin resistant individuals compared to insulin sensitive individuals, and has been directly associated with whole‐body insulin resistance and high fasting plasma glucose." (PMID 32562350, 2020). "Another possible reason to this relation is that patients who require a higher amount of insulin could have an underlying condition causing insulin resistance." (PMID 32832557, 2020).
Insulin resistance (continued). "Curcumin mediated reduction in the insulin levels and insulin resistance (HOMA-IR) could reduce the risk factors for cognitive impairment such as neuritic plaques and amyloid formation." (PMID 32283762, 2020). "Notably, cumulative methylation across 14 CpGs of INSR promoter in GSAT was associated with higher insulin resistance (insulin concentrations and HOMA-IR) and lower adiponectin concentrations in black women." (PMID 33133129, 2020). "While a few insulin resistance genes have been identified, the underlying genetic architecture of insulin resistance remains unknown." (PMID 33362275, 2020). "Increased adiposity causes insulin resistance resulting in a subsequent rise in insulin levels." (PMID 33312198, 2020). "Intracellular stresses such as reactive oxygen species, ceramide, and protein kinase C (PKC) isoforms could modulate insulin signaling via the activation of NFκB and cause insulin resistance." (PMID 32911750, 2020). "Intriguingly, studies have reported that psoriasis is an independent risk-factor for T2D and insulin resistance, separate from underlying obesity, with the severity of psoriasis correlating with increased likelihood of developing T2D and the requirement of insulin therapy." (PMID 32599074, 2020). "The activated ProINS-Tf, serving as a bivalent protein molecule, could be a new insulin analog to overcome insulin resistance, which is associated with several diseases, including type 2 diabetes and non-alcoholic fatty liver disease." (PMID 32382087, 2020). "Importantly, while sleep deprivation alone induces insulin resistance in controlled laboratory experiments, circadian misalignment causes additive impairment of insulin sensitivity even with sleep time kept constant at a meager 5 h." (PMID 32363197, 2020). "Besides the glucose-lowering effect, animal studies have demonstrated that ASX improves insulin sensitivity and glucose uptake, thereby lowering insulin resistance, the hallmark of T2DM." (PMID 32660119, 2020). "Impaired insulin secretion is caused by stimulating adrenergic α2 receptors of pancreatic β-cells and increased insulin resistance is caused by stimulating adrenergic α1 and β3 receptors in adipocytes, α1 and β2 receptors of pancreatic α-cells and skeletal muscle." (PMID 33324347, 2020). "Moreover, the causal effect of overall obesity on fasting insulin and insulin resistance is slightly greater than that of abdominal obesity." (PMID 32714368, 2020). "While several factors such as exercise, oxidative stress and inflammation modulate insulin action, the pathological levels of insulin resistance associated with metabolic disease are driven by chronic overnutrition and ectopic fat accumulation in target tissues." (PMID 32574288, 2020). "However, M-LRP2−/− mice had a higher risk for insulin resistance, as revealed by higher serum insulin levels in the fasting state." (PMID 32332780, 2020). "HFD-induced obesity was associated with high fasting glucose and insulin concentrations, suggesting that a high degree of obesity in these animals might be caused, in part, by high insulin resistance." (PMID 32872540, 2020). "The pathway’s sensitivity to insulin may be blunted by many factors such as free fatty acids, causing insulin resistance." (PMID 32365816, 2020). "Therefore, mediating factors associated with the insulin signaling pathways can be a therapeutic target for improving insulin resistance of T2DM." (PMID 33266423, 2020). "However, precursors of TAGs and DAGs are associated with hepatic insulin resistance through the induction of protein kinase Cε, which results in the inhibition of insulin signaling." (PMID 32796572, 2020). "Therefore, IMCL accumulation increases the risk of insulin resistance in aging skeletal muscle by impairing the insulin signaling pathway or promoting the inflammatory pathway." (PMID 32082422, 2020).
Insulin resistance (continued). "LRYGB was in our study associated with a reduction in fasting insulin, HbA1c, and fasting glucose levels as well as improvement in insulin resistance, not only in the diabetic group but also for all patients irrespective of glucometabolic state at the time of surgery." (PMID 32314253, 2020). "Ectopic fat that is localized to major glucose regulatory organs such as the liver, skeletal muscle, and pancreas is commonly regarded as being “lipotoxic,” since this ectopic fat can interfere with normal insulin signaling and promote insulin resistance and increase the risk for T2D." (PMID 32158768, 2020). "However, excessive alcohol uptake also increases the risk for insulin resistance, which is characterized by the inability of insulin-sensitive tissues to respond to insulin, resulting in various metabolic syndromes." (PMID 32508647, 2020). "When present in excess, it could antagonize the role of insulin and reduce the sensitivity of tissues and organs to insulin, which causes insulin resistance." (PMID 32850735, 2020). "Insulin resistance is characterized by the deficiency in metabolic actions of insulin." (PMID 32610588, 2020). "It is possible that shared microbe-host responses potentiate insulin secretion and impair insulin clearance, which could increase the insulin load over time and increase the risk of complications from hyperinsulinemia, including obesity and insulin resistance." (PMID 32860984, 2020). "Actually, JNK can be activated in various tissues by high levels of cytokines and FFA and has been implicated in obesity-induced insulin resistance and insufficient compensatory insulin secretion, two key features of type 2 diabetes, and also associated with diabetic complications." (PMID 33143088, 2020). "However, in type 2 diabetic patients, L-sulforaphane-rich broccoli sprout powder caused a significant improvement in serum insulin concentration, glucose-to-insulin ratio, and insulin resistance." (PMID 33123312, 2020). "One setback of early insulin therapy, however, is that it is associated with hyperphagia, weight gain and lipogenesis, which could exacerbate the insulin resistance and the metabolic alterations observed in T2D and lead to intensified treatment." (PMID 32150819, 2020). "When evaluating insulin resistance there was a significant interaction in the association of fasting insulin with % CD14++CD16− (classical) monocytes (p = 0.0365) and HOMA-IR (p = 0.0403), due to a significant association in the other race category (p = 0.0383 and 0.0277, respectively)." (PMID 32528415, 2020). "Peripheral insulin resistance could induce insulin signaling disorders in the central nervous system and cause neuronal death and reduce synapse plasticity in the hippocampus." (PMID 32575897, 2020). "Our results showed that increased leptin levels may be associated with insulin resistance because leptin levels were positively correlated with fasting serum insulin levels and HOMA‐IR index and negatively with QUICKI." (PMID 31914480, 2020). "Insulin resistance, which is known to often co-exist with obesity, might also have a role in augmented estrogen levels through interaction in insulin signaling pathways, possibly causing exogenous estrogen synthesis." (PMID 32351453, 2020). "Another report demonstrated that plasma SAM levels were associated with cardiometabolic risk factors such as higher fasting insulin levels, homeostasis model assessment of insulin resistance and TNF-α in a cross-sectional study in humans with metabolic syndrome." (PMID 32145700, 2020). "In addition, we observed that beyond a certain threshold, those with a greater degree of underlying insulin resistance or β-cell function had greater intervention-induced reductions in postprandial insulin." (PMID 33308235, 2020). "Further studies found that TNFα can perturb insulin signaling, causing insulin resistance." (PMID 32183037, 2020).